CASQ2 (calsequestrin 2)
Diseases named in the same sentence as CASQ2 in open-access papers (continued):
Sharing a sentence is not in itself a finding about the gene and the disease.
heart failure (9 papers, 2015 to 2024). Inability of the heart to pump blood at an adequate rate to meet tissue metabolic requirements. "In a study on dogs with tachypacing-induced heart failure, high CASQ2 turnover was linked to increased muscle damage." (PMID 39175772, 2024). "In the heart, the defective glycosylation of CASQ2 has been linked to acquired cardiac diseases; Man8,9-containing CASQ2 is highly increased in the heart failure of different etiologies, and it is worth mentioning that the protein is concomitantly more phosphorylated." (PMID 38136565, 2023). "In support of this hypothesis, defective or altered canine Casq2 phosphorylation is associated with several muscular complications, including heart failure." (PMID 27649144, 2016). "Except that of calsequestrin-2, the expression of others decrease in various experimental models of CH and heart failure and in human patients." (PMID 31920643, 2019). "The Casq2-/- mice, a known model of cardiac insufficiency ran longer than healthy WT controls during the PXTm." (PMID 26859763, 2016). "Thus, this response was replicated with the GXTm in the genetic model of cardiac insufficiency (9.32 ±1.53mmol/L, Casq2-/- v." (PMID 26859763, 2016). "Recent studies suggest that variants in two calcium handling genes (RyR2 and CASQ2) associated with sudden cardiac death (SCD) and non-sudden cardiac death (NSCD) in subjects with heart failure and coronary artery disease, respectively." (PMID 26196381, 2015). "Although the total levels of CASQ2 do not appear to be altered in cardiac hypertrophy or heart failure, alterations in the post-translational glycosylation or phosphorylation of CASQ2 protein were observed in a heart failure model." (PMID 28886186, 2017).
sudden cardiac death (5 papers, 2015 to 2022). "For example, a literature review evaluated and summarized the effect of 53 SNPs on sudden cardiac death (SCD) and found that rs6684209, rs3814843, and rs35594137 in CASQ2, CALM1, and GJA5, respectively, had the most significant association with SCD." (PMID 34912794, 2021).
ventricular tachycardia (5 papers, 2010 to 2025). A disorder characterized by an electrocardiographic finding of three or more consecutive complexes of ventricular origin with a rate greater than a certain threshold (100 or 120 beats per minute are commonly used). "The gene CASQ2, encoding the calcium-binding protein, played a crucial role in excitation-contraction coupling, regulated the heart rate, and was associated with ventricular tachycardia." (PMID 35924220, 2022). "The disruption of CASQ2, essential for Ca2+ storage, led to ventricular tachycardia in both mice and humans." (PMID 35924220, 2022). "Ivabradine poorly prevented the ECG arrhythmic features of CASQ2-D307H KI mice, where at rest three out of six mice still exhibited ventricular tachycardia or premature ventricular complexes." (PMID 32009964, 2019). "During treadmill exercise, ivabradine was completely ineffective since all six ivabradine-treated CASQ2-D307H KI mice showed ventricular tachycardia." (PMID 32009964, 2019).
atrial fibrillation (4 papers, 2017 to 2023). A disorder characterized by an electrocardiographic finding of a supraventricular arrhythmia characterized by the replacement of consistent P waves by rapid oscillations or fibrillatory waves that vary in size, shape and timing and are accompanied by an irregular ventricular response. "rs4484922 and rs4074536 in calsequestrin 2 (CASQ2) gene were in high LD and were reported to be associated with QRS duration and atrial fibrillation, which was also replicated by our finding." (PMID 34912794, 2021). "This extended gene network contained a number of transcription factors (Tbx5, Hand2, Fhl2, and Gata4) and ion/calcium handling genes (Ank2, Cacna2d2, Scn5a, Kcnd2, Kcnj5, Myoz2, Casq2, Csrp3, and Gja3) of interest in the context of atrial fibrillation." (PMID 28720711, 2017).
cardiomyopathy (4 papers, 2013 to 2025). A disease of the heart muscle or myocardium proper. "Interestingly, both RyR2 and CASQ2 mutations may be responsible for cardiomyopathies." (PMID 23476865, 2013). "Data analysis also indicated that there are many genes related to cardiomyopathy, such as TTN, NEFH, PLEC, CASQ2, and SYNE1." (PMID 33200202, 2020).
polymorphic ventricular tachycardia (4 papers, 2017 to 2023). A ventricular tachycardia that is irregular in rate and rhythm. "In a study on CPVT, it was mentioned that SK4 channel blockers protected calsequestrin 2 (CASQ2, the gene predisposing to CPVT), CASQ2-D307H KI and CASQ2 KO mice from deleterious polymorphic ventricular tachycardia (PMVT)." (PMID 36975511, 2023). "CASQ2 seems to play a role in catecholaminergic polymorphic ventricular tachycardia research." (PMID 31991631, 2020). "The SK4 channel blockers protected the CASQ2‐D307H KI and CASQ2 KO mice from harmful polymorphic ventricular tachycardia without being pro‐arrhythmic by themselves, since neither sinus arrest nor second‐order AV block was recorded in the animals, including WT mice." (PMID 28219898, 2017).
Bradycardia (3 papers, 2015 to 2021). A slower than normal heart rate (in adults, slower than 60 beats per minute). "Under basal conditions and during treadmill exercise, bradycardia and PR prolongation were noticed in CASQ2‐D307H KI and CASQ2 KO mice following clotrimazole injection." (PMID 28219898, 2017). "The phenotype included bradycardia, RR interval variability, SAN conduction abnormalities, and abnormally high atrial ectopic activity resulting in AF, implicating calsequestrin-2 in SAN functioning." (PMID 33868385, 2021). "In CASQ2 null mice, reduced CASQ2 expression in nodal cells led to decreased SBR and sinoatrial bradycardia, similar to DEHP’s effect on hESC-CM shown here." (PMID 25799571, 2015). "Intraperitoneal injection (20 mg/kg) of SK4 channel blockers, TRAM‐34 or clotrimazole, elicited bradycardia and noticeably reduced the ECG arrhythmic features recorded in vivo from CASQ2‐D307H KI and CASQ2 knockout (KO) mice at rest and following treadmill exercise." (PMID 28219898, 2017).
breast carcinoma (3 papers, 2022 to 2025). "We also noted the upregulation of CASQ2, the overexpression of which was recently associated with a more aggressive form of breast cancer." (PMID 40004168, 2025). "Previous studies have shown that CASQ2 has a significant impact on several cellular processes associated with breast cancer, including the proliferation, migration and invasion." (PMID 38143739, 2023). "The overexpression of CASQ2 in breast cancer cells was also associated with increased intracellular calcium signaling." (PMID 34743414, 2022). "We further explored the association between the expression level of CASQ2 and breast cancer molecular subtypes as the spatial shape of breast cancer is related to the subtype." (PMID 34743414, 2022). "CASQ2 further affected the patterns of collagen rearrangement within the microenvironment, which has been linked to the more aggressive features of breast cancer." (PMID 34743414, 2022). "As CASQ2 was demonstrated to cause the most distinct phenotypic changes in Hs578T cells among several breast cancer cell lines examined, we hypothesized that the expression of CASQ2 could be associated with the features of human metaplastic carcinoma." (PMID 34743414, 2022). "Our data suggest that CASQ2 is a key regulator of breast cancer tumorigenesis and metastasis by modulating diverse aspects of tumor–microenvironment interactions." (PMID 34743414, 2022). "In this study, we identified CASQ2 as an important gene regulating various aspects of breast cancer progression." (PMID 34743414, 2022). "To evaluate the role of CASQ2, we established CASQ2‐overexpressing breast cancer cell lines for in vitro and in vivo experiments." (PMID 34743414, 2022). "We showed that CASQ2, a gene previously considered to be involved in cardiac function, is an important regulator of breast cancer progression and metastasis." (PMID 34743414, 2022). "To investigate the effect of CASQ2 on breast cancer metastasis, we injected cells into the tail vein of NSG mice." (PMID 34743414, 2022). "Together, these data indicated that CASQ2 regulates the transition of the hypoxia‐induced phenotype in breast cancer cells, supporting its role in the process of distant metastasis." (PMID 34743414, 2022). "The expression of CASQ2 was further increased in mammosphere and was also associated with increased level of CD44, a well‐known marker of breast cancer stem cells." (PMID 34743414, 2022). "Overexpression of CASQ2 in breast cancer cells resulted in more aggressive phenotypes and dysregulation of intracellular signaling pathways, along with increased tumorigenesis and remodeling of collagen structures." (PMID 34743414, 2022). "CASQ2 overexpression in breast cancer cells resulted in a more aggressive phenotype and altered epithelial–mesenchymal transition (EMT) markers in vitro." (PMID 34743414, 2022). "We analyzed gene expression and three‐dimensional tumor shape data from the breast cancer dataset of The Cancer Genome Atlas (TCGA) and identified CASQ2 as a potential regulator of tumor–microenvironment interaction." (PMID 34743414, 2022). "To determine the functional importance of CASQ2 in breast cancer, we established various CASQ2‐overexpressing breast cancer cell lines." (PMID 34743414, 2022). "The role of CASQ2 in human breast cancers, as well as the influence of calcium modulation on the effect of anticancer agents, should be further explored." (PMID 34743414, 2022). "To investigate the role of CASQ2 in breast cancer tumorigenesis, we injected control and CASQ2‐overexpressing Hs578T or MDA‐MB‐231 cells into the mammary fat pads of female NSG mice." (PMID 34743414, 2022). "Here, we investigated the role of a newly identified breast cancer‐related gene, calsequestrin 2 (CASQ2), in tumor–microenvironment interactions during tumor growth and metastasis." (PMID 34743414, 2022).
breast carcinoma (continued). "Together, these data suggest that CASQ2 promotes the growth of breast cancer and regulates various aspects of the TME, including the adjacent collagen structures and fibroblast education, potentially resulting in differences in spatial tumor growth." (PMID 34743414, 2022). "In TCGA breast cancer cases containing information of three‐dimensional tumor shapes, CASQ2 mRNA showed the highest correlation with the spatial tumor shapes." (PMID 34743414, 2022). "Next, we performed immunohistochemical staining of human breast cancer tissues to determine the pattern of distribution of CASQ2." (PMID 34743414, 2022). "Together, these data indicated that CASQ2 might be a major regulator of breast cancer differentiation toward metaplastic features." (PMID 34743414, 2022). "CASQ2 also mediates various aspects of TME interactions in breast cancer." (PMID 34743414, 2022). "We evaluated the expression level of CASQ2 in various breast cancer cell lines." (PMID 34743414, 2022). "Both human breast cancer cells and normal mammary epithelial cells expressed CASQ2." (PMID 34743414, 2022). "Our findings suggest that breast cancer cells may undergo dynamic changes in calcium signaling in vivo via the induction of CASQ2, which may in turn regulate the stem cell properties during tumor growth and metastasis." (PMID 34743414, 2022). "Additionally, we measured the CASQ2 mRNA level in the SNUH 143 patient cohort and observed that the high CASQ2 level is related to tumor irregularity in luminal A and basal type of breast cancer." (PMID 34743414, 2022). "We found that CASQ2 was also expressed in fresh frozen‐resected breast cancer tissues." (PMID 34743414, 2022). "Our data show that CASQ2 can promote the growth and metastasis of breast cancer cells." (PMID 34743414, 2022). "Together, these findings indicated that CASQ2, a factor previously considered to be involved in cardiac functions, might also regulate various biological aspects of the breast cancer cell physiology and affect the cancer phenotype in vitro." (PMID 34743414, 2022). "Furthermore, we investigated the expression pattern of CASQ2 in human breast cancer tissues." (PMID 34743414, 2022). "Interestingly, breast cancer tissues exhibited a heterogeneous pattern of expression of CASQ2." (PMID 34743414, 2022). "Additionally, our in vitro data suggest that CASQ2 may have different biological significance in various breast cancer cell lines suggesting the cell type‐specific function of CASQ2." (PMID 34743414, 2022). "Thus, CASQ2 conclusively conferred breast cancer cells with more metaplastic features." (PMID 34743414, 2022). "Notably, the expression of CASQ2 and ALDH1, another breast cancer stem cell marker, was increased in the mammosphere culture condition." (PMID 34743414, 2022). "We specifically observed that the overexpression of CASQ2 did not induce major morphological changes in breast cancer cells, but promoted cell proliferation in multiple cell lines." (PMID 34743414, 2022). "Although various breast cancer cell lines displayed varying degrees of CASQ2 mRNA expression with relative fold changes, the actual mRNA expression levels were very low (data not shown), and we also did not determine the level of CASQ2." (PMID 34743414, 2022). "Therefore, we tested the expression of various EMT‐related proteins in breast cancer cells and observed that the levels of several EMT markers, including slug, snail, and vimentin, were increased in CASQ2‐overexpressing cells and the level of ZEB1 was decreased." (PMID 34743414, 2022).
cardiac arrest (3 papers, 2021 to 2023). Cessation of breathing and/or cardiac function. "When the proband was initially diagnosed with CPVT following her cardiac arrest, exons of RyR2 encompassing hot spot mutations and all coding exons of CASQ2 and TRDN were first screened, but no variant was found." (PMID 34202968, 2021). "In addition, despite no statistical significance, patients with CASQ2 mutations appeared to suffer from a lower rate of cardiac arrest and mortality rate compared to those with RYR2 mutations." (PMID 38053087, 2023).
cardiac hypertrophy (3 papers, 2017 to 2023). "In contrast, transgenic mice that overexpress CASQ2 develop cardiac hypertrophy." (PMID 28886186, 2017). "Overall, these results suggest that the genetic inhibition of mPTP in the CPVT model of CASQ2 KO did not lead to overt pathological cardiac remodeling, despite some early signs of potential cardiac hypertrophy." (PMID 36672139, 2023).
channelopathy (3 papers, 2021 to 2023). Channelopathies are a group of diseases caused by the dysfunction of ion channel subunits or their interacting proteins. "It is classified as channelopathy, indicating a gene mutation that translates to specific ion channels in the cardiac myocytes, namely ryanodine receptor-2 (RyR2) and calsequestrin-2 (CASQ2) channels." (PMID 38034271, 2023). "The deceased participant with a channelopathy variant had a heterozygous CASQ2 variant." (PMID 35544069, 2022).
diabetes (3 papers, 2013 to 2025). "A diabetes-specific targeted analysis showed negatively enriched Z-disc and contractile gene sets enriched due to the downregulation of CASQ2, peripherin (PRPH), nebulette (NEBL), titin-cap (TCAP), and LIM domain-binding proteins LDB3, PDLIM4, and PDLIM5 (Dataset EV36)." (PMID 40759793, 2025). "The five increased calcium genes (Myl6b, Casq2, Itga7, Cacnb2 and Sln) have not had changed expression in previous diabetes studies." (PMID 24199937, 2013).
Obesity (3 papers, 2016 to 2025). Accumulation of substantial excess body fat. "We used lean WT (C57BL/6J) male mice as a control group, C57BL/6J male mice with diet induced obesity (WT-Obese) as a non-transgenic model of cardiac deficiency, and calsequestrin 2 (cardiac isoform) deficient (Casq2-/-) male mice as a genetic model with reported cardiac deficiency." (PMID 26859763, 2016).
ventricular fibrillation (3 papers, 2010 to 2024). A disorder characterized by an electrocardiographic finding of a rapid grossly irregular ventricular rhythm with marked variability in QRS cycle length, morphology, and amplitude. "Genetic testing is recommended for CPVT-susceptibility genes—RyR2, CASQ2, CALM1-3, TRDN and TECRL—in all probands with a definitive clinical diagnosis of CPVT and may be considered in individuals with idiopathic ventricular fibrillation (VF) upon identification of an adrenergic trigger." (PMID 38542006, 2024).
atrial fibrillation/flutter (2 papers, 2021). "Atrial burst pacing induced atrial flutter and AF in Casq2–/– mice versus wild-type (WT) mice, and isolated Casq2-deficient hearts showed ectopic foci from the pulmonary vein region when visualized with atrial optical voltage maps." (PMID 33868385, 2021).
dilated cardiomyopathy (2 papers, 2017 to 2022). Cardiomyopathy which is characterized by dilation and contractile dysfunction of the left and right ventricles. "This is supported by findings from a previous study in which overexpression of Casq2 with 10-fold higher levels in the heart caused severe dilated cardiomyopathy and premature death." (PMID 35167494, 2022). "On the contrary, transgenic mice with Casq2 overexpression in cardiomyocytes had severe dilated cardiomyopathy and died prematurely by age 16 weeks." (PMID 35167494, 2022).
Hypertension (2 papers, 2021 to 2024). The presence of chronic increased pressure in the systemic arterial system. "Two of the recurrent AF genes also code for functions directly or indirectly linked to AF (CASQ2 and GOSR2), and some genes indicate a possible indirect link related to comorbidities, e.g., hypertension or malignancy (PPFIA4, USP34, WIPF1, SPATS2L, CAND2, and AOPEP)." (PMID 38725839, 2024).
Sinus bradycardia (2 papers, 2019 to 2023). Bradycardia related to a mean resting sinus rate of less than 50 beats per minute. "Most CPVT patients demonstrate a prominent sinus bradycardia in resting ECG, which may result from the diastolic calcium leakage from the ryanodine receptor, resulting from either RyR2 or CASQ2 mutations." (PMID 38053087, 2023).
Supraventricular tachycardia (2 papers, 2019 to 2022). Supraventricular tachycardia (SVT) is an abnormally increased heart rate (over 100 beats per minute at rest) with origin above the level of the ventricles. "One Casq2 KO mouse had no PVCs but had supraventricular tachycardia immediately after catecholamine injection, an observation we have noted may protect these mice from ventricular ectopy." (PMID 34990403, 2022).
congestive heart failure (1 paper, 2018). Failure of the heart to pump a sufficient amount of blood to meet the needs of the body tissues, resulting in tissue congestion and edema. "Moreover, Casq2 reduction has also been observed in the atrial myocytes of congestive heart failure patients that are associated with risk of AF." (PMID 30450052, 2018).
coronary artery disease (1 paper, 2015). "A previous study has revealed 3 SNPs associated with SCD in patients with coronary artery disease: CASQ2 region (rs17500488, rs3010396, and rs7366407)." (PMID 26196381, 2015).
hypertrophic cardiomyopathy (1 paper, 2023). "To this end, we conducted gene enrichment analysis, and observed stronger enrichments of upregulated genes involved in hypertrophic cardiomyopathy (ADRA1A, TNNI3, MYL2) and cardiac muscle contraction (CACNA1C, CASQ2, CAMK2B)." (PMID 37084237, 2023).